RN7SL717P (RNA, 7SL, cytoplasmic 717, pseudogene)
Gene: Miscellaneous RNA gene on chromosome 2 (199,901,081 to 199,901,377, reverse strand). Ensembl gene ENSG00000240302.
Homologues: Orthologues: chimpanzee Metazoa_SRP (99% identical), macaque Metazoa_SRP (82% identical). Paralogues in human: RN7SL1 (84% identical), RN7SL3 (84% identical), RN7SL2 (83% identical), RN7SL118P (81% identical), RN7SL230P (81% identical), RN7SL786P (81% identical), RN7SL220P (80% identical), RN7SL664P (80% identical), RN7SL709P (80% identical), RN7SL126P (80% identical), RN7SL333P (80% identical), RN7SL357P (80% identical), and 706 more.